TNF (tumor necrosis factor)
Diseases named in the same sentence as TNF in open-access papers (continued):
Sharing a sentence is not in itself a finding about the gene and the disease.
breast carcinoma (continued). "We investigated the association between 89 single nucleotide polymorphisms (SNPs) in 7 cytokine/growth-factor genes (FGFR2, IGFBP1, IGFBP3, TGFB1, TNF, VEGF, IL6) and percent MD in 301 premenopausal women (aged 50 to 55 years) participating in the Norwegian Breast Cancer Screening Program." (PMID 23762340, 2013). "We tested the Tfsitescan predictions by treating cultured representative breast cancer cell line, MDA MB 231, for 24 h with known activators for NFκB (TNF-α), NFAT (PMA or ionomycin), GR (dexamethasone), and AP1 (PMA) and measuring the levels of each mRNA by qRT-PCR." (PMID 23342266, 2012). "To study the release of the two chemokines CXCL9 and CXCL10 from breast cancer cells we investigated regulation of protein secretion by supplying the inflammatory cytokines IFN-γ and TNF-α, which are both present in breast cancer tissues and known to induce CXCR3 ligands in other cell types." (PMID 22333315, 2012). "No other significant differences were found between the different groups of breast cancer patients with respect to TNFα and IL-1β expression in the tumor cells (namely: IDC-no-relapse vs. DCIS; IDC-no-relapse vs. IDC-with-relapse)." (PMID 21486440, 2011). "Maximum induction of uPA RNA was seen at 6 hours post TNF-α stimulation in fascin-positive breast cancer cells, while fascin-knockdown cells failed to induce significant up-regulation compared with the control cells." (PMID 22076152, 2011). "Although antimycin, TNF-α, and photodynamic therapy are not used in the treatment of breast cancer, adriamycin and ionizing radiation are extensively used." (PMID 20532186, 2010). "In addition, the induction of TNFα and TNF-receptor I in breast cancer cells mediated by ANT2 shRNA generates the bystander effect that leads necrosis to the adjacent cells." (PMID 18267033, 2008). "In a breast cancer xenograft model, locally injected recombinant human TNF-alpha arrested growth of established tumours in the absence of overt necrosis." (PMID 7577463, 1995). "We conclude from these observations that combined therapy with rHu-TNF and rat IFN-gamma may prove to be useful new forms of treatment for human breast cancer." (PMID 2495016, 1989). "Furthermore, TRAF3-expressing breast cancer cells displayed reduced levels of PD-L1 and when co-cultured with PBMCs induced a pro-inflammatory profile with increased CD16-NK cells and higher levels of IFN-γ and TNF-α and lower IL-10 and Tregs in the culture." (PMID 42196397, 2026). "Skimmianine-mediated TNF-α suppression may contribute to decreased inflammation and immune evasion, aligning with studies showing that TLR4 targeting decreases proliferation and cytokine secretion in breast cancer cells." (PMID 40430573, 2025). "To date, no clinical evidence supports using TNF inhibitors in breast cancer." (PMID 41007766, 2025). "Within the breast cancer microenvironment, exosomes containing ANXA2 stimulate the activation of MAPK and NF-κB signaling pathways in macrophages, thereby mediating the secretion of the chemokines IL-6 and TNF-α to remodel the microenvironment to support breast cancer cell survival." (PMID 39972459, 2025). "Additionally, two small randomized controlled trials looking at inflammatory markers in breast cancer survivors demonstrated that aerobic and resistance-based exercise programs reduced inflammatory markers, such as C-reactive protein (CRP) and tumor necrosis factor alpha (TNF-α), respectively." (PMID 41283543, 2025). "Furthermore, doubling the concentrations of TNF on RH30 IκBα-SR cells did not significantly increase cell death compared to similarly treated MDA231 IκBα-SR breast cancer cells." (PMID 40799389, 2025). "Nonetheless, the qualitative consensus in recent reviews is that TNF-α contributes to breast cancer progression and could be a negative prognostic factor." (PMID 41007766, 2025).
breast carcinoma (continued). "Moreover, IFN-γ, IL-1β, and TNF-α are key cytokines released by cytotoxic CD8+ TEff cells; in vitro exposure to IFN-γ, IL-1β, and TNF-α induced cellular elongation, migration, and invasion of ER– MDA-MB-231 breast cancer cells, which were limited by NOS/COX inhibitors." (PMID 40663402, 2025). "Notably, Antro did not affect TNF-α production in M1 macrophages, and similar findings were observed in breast cancer cell lines." (PMID 41509543, 2025). "In flow cytometry, cocultures of the breast cancer cell lines with M13SV1_DSP8-11 wild-type or M13SV1_ASCT2KO_DSP8-11 cells yielded in zero to low amounts of green fluorescent cells, which were not significantly altered by addition of TNFα." (PMID 38891857, 2024). "TNFα was predicted to have a 48% increase in breast cancer compared to no cancer in our model." (PMID 38541912, 2024). "Although it is known that TGF-β or TNF-α stimulation regulates the MMP-9 expression in various cells, it remains unclear how the combined TGF-β/TNF-α stimulation modulates MMP-9 expression in breast cancer cells." (PMID 39351229, 2024). "However, there was a trend that obese patients with breast cancer were more likely than nonobese patients to have higher levels of TNF-α, MIP-1α, and M-CSF (P <0.10)." (PMID 39440056, 2024). "We hence concluded that mast cell-derived TNF and/or cancer cell TNF triggered by mast cell-derived soluble factors is essential to stimulate the MUC1/estrogen receptor axis and promote the stem-like properties, eventually increasing the aggressiveness of mammary cancer cells." (PMID 39349458, 2024). "TGF-β and TNF-α, pro-inflammatory cytokines that are extensively expressed in the tumor microenvironment, upregulate the LOX expression via the reactive oxygen species–activated NF-κB/extracellular signal-related kinase pathway, thus promoting the progression of breast cancer metastasis." (PMID 35138531, 2023). "There was little evidence of an effect of cytokines, including TNFα and IL6, on breast cancer risk." (PMID 36867866, 2023). "Similarly, an in vitro analysis study revealed no obvious impacts on TNF-α release during different types of anesthesia for breast cancer surgery." (PMID 36765695, 2023). "TNF-α treatment could switch the non-CSC (CD44+/CD24+) population to a CSC-like (CD44+/CD24−) population by increasing the expression of EMT factors in breast cancer cells." (PMID 36979874, 2023). "Knowing that TNF-α activates NF-κB signaling by binding to the TNFR1 receptor, we hypothesized that the ETV7-mediated repression of TNFRSF1A modulates the transcriptional activity of NF-κB in MCF7 and T47D breast cancer cells." (PMID 37041130, 2023). "In addition, CAAs can also secrete chemokine ligand 2 (CCL2), chemokine ligand 5 (CCL5), and interleukin-1β (IL-1β), Interleukin-6 (IL-6), tumor necrosis factor-α (TNF-α), vascular endothelial growth factor (VEGF) and leptin, which can promote the invasion and metastasis of breast cancer." (PMID 37305043, 2023). "In a tumor model based on harvested macrophages and breast cancer cells from Swiss albino mice, hBD-2 treatment of the macrophages increased the expression of inflammatory cytokines (IFN-γ, interleukin 1α (IL-1α) and tumor necrosis factor α (TNF-α)) and chemokines (CXCL1, CXCL5 and CCL5)." (PMID 36982340, 2023). "CX3CL1 and CXCL13 were shown to play an important role in the brain extravasation of breast cancer, while the following cytokines/chemokines were involved in the extravasation of melanoma cells (9IL-23, CXCL10, CXCR3, CXCL10 receptor, CCR4, CCL17, and CCR4) and lung cancer cells (TNF-α and CX3CR1)." (PMID 37190188, 2023). "Most biological functions in the MCF7 network are controlled by the PIK3R1 gene, and many other pathways, including apoptosis, ErbB, JAK–STAT, HIF-1, the control of the actin cytoskeleton, TNF, cancer-related pathways, TCR, BCR, and TLR signaling pathways, may also be related to breast cancer." (PMID 36675976, 2022).
breast carcinoma (continued). "However, to our knowledge, no prior study has revealed an LPA-induced TNF-alpha secretion in breast cancer cells." (PMID 35365723, 2022). "Additionally, AFI has been reported to have anticancer activities against human breast cancer cells (MCF-7) and lung cancer cells (HCC827) by stimulating the production of tumor necrosis factor-alpha (TNF-α), interleukin-6 (IL-6), and interleukin-1 beta (IL-1β)." (PMID 36059847, 2022). "Despite the tumor‐promoting role of TNF‐α in breast cancer, only a handful of studies have attempted to decipher the mechanism of TNF‐α in driving breast cancer progression, and NF‐κB appeared to be an integral component of TNF‐α‐induced breast cancer aggressiveness." (PMID 34197030, 2022). "Similarly, voluntary wheel running for 4 weeks in breast cancer mice (PyMT) decreases not only circulating but intramuscular levels of TNF-α protein, as well as reduces the intramuscular mRNA content of several TNF-α target genes (Traf2, IκB-α, Ank1 and NFκB1)." (PMID 35626116, 2022). "A recent study on the role of NPD-L1 and TNFα in breast cancer showed that under hypoxia, PD-L1 can migrate to the nucleus and activate GSDMC, which is then cleaved by the TNFα activated-caspase-8, triggering pyroptosis and promoting the death of breast cancer cells." (PMID 35359956, 2022). "In the murine 4T1 breast cancer model, administration of Tβ4 and TGF-β1 decreased the sJAM-A levels in murine blood, and a peptide derived from the sequence of the F11R/JAM-A protein, peptide 4D (P4D), blocked the TEM of breast cancer cells in the presence of TNF/IFN and Tβ4." (PMID 35356274, 2022). "However, mammary carcinoma cells responded to poly(I:C) transfection with the upregulation of Cxcl10 and IL-6 but not TNFα mRNA levels." (PMID 35737804, 2022). "As previous study has reported that blocking of STAT3 in breast cancer cells induced an antitumor immune response involving CD4+ T cells, which may ameliorate TME via secretion of cytokines, such as TNF-α, IFN-γ, IL-6, and IL-5, as well as chemokines CCL5 and CXCL10." (PMID 33957948, 2021). "TNF-α signaling may thereby play an important role in producing depressive symptoms, consistent with prior work linking sTNF-RII with cognitive complaints and fatigue in women with breast cancer." (PMID 34873150, 2021). "Next, in addition to TNF-α, the changes in IFN-γ and its receptors (IFN-γ-Rα/β) are gaining wider interest due to their modulatory effects on cell growth/differentiation and inflammatory responses and also for being a potential therapeutic tool in breast cancer." (PMID 34572567, 2021). "Since we observed that GPx1 deficiency enhanced TNF-α-induced apoptosis of MCF7 (luminal A type and RIPK3-negative) cells, the antiapoptotic function of GPx1 is thought to be independent of the molecular subtype of breast cancer." (PMID 34158609, 2021). "LCL161 sensitivity patterns were supported by mechanistic analyses of the drug targets and TNF-α signaling, indicating target engagement and a potential for response prediction by RIPK1 gene expression levels, consistent with previously published clinical data in breast cancer." (PMID 34496878, 2021). "Similarly, the combination of TNFSF4 (OX40L) fusion protein and poxvirus-based cancer vaccine (MVA-Twist-TRICOM) can also be used effectively to inhibit lung metastasis of breast cancer by increasing the infiltration of CD4+CD8+ T cells and the production of IFN-γ and TNF-α." (PMID 34367975, 2021). "Therefore, it would be of further interest to see whether the co-stimulation with TNF-α and IFN-γ may have a synergistic effect on IP-10 induction in breast cancer and other cell types." (PMID 34572567, 2021). "Tumor necrosis factor-α (TNF-α) is an immunostimulatory cytokine that is consistently high in the breast tumor microenvironment (TME); however, its differential role in mitochondrial functions and cell survival in ER/PR +ve and ER/PR −ve breast cancer cells is not well understood." (PMID 33926547, 2021).
breast carcinoma (continued). "Using RT-PCR to examine expression levels of genes in circulating leukocytes, it was shown that TNF-alpha, IL-6, leptin and ErbB2, were significantly higher in obese individuals without a cancer diagnosis and among breast cancer patients compared to the lean group." (PMID 33597950, 2020). "To confirm whether TNF-α promotes breast cancer stem-like cells, we cultured MCF7 cells under non-adherent culture conditions to foster mammosphere formation and found that TNF-α addition (10 ng/ml) significantly increased the number of mammospheres." (PMID 32019974, 2020). "This gives rise to the possibility that EGR-1-dependent signaling loop and the TNFα-EGR-1–CYP19–estrogen-EGR-1 axis could result in persistent activation of estrogen production, thereby facilitating the development of ER-positive breast cancer in the tumor microenvironment." (PMID 33053908, 2020). "Interestingly, the phenomenon of TNF-α-induced activation of caspases was only detected in the ERα-positive MCF-7 human breast cancer cells, and not in the ERα-negative MDA-MB-231 human breast cancer cells." (PMID 32455774, 2020). "We pretreated the BEAS‐2B and breast cancer (MDA‐MB‐231) cells with TDZ and deliberated alteration in a cell viability, mammosphere, migration, NF‐кB signalling, PI3K/AKT signalling and matrix metalloproteinase (MMP) expression and analysed the EMT induction by TGF‐β/TNF‐α‐stimulated BEAS‐2B cells." (PMID 33159487, 2020). "Breast cancer cells direct the tumor angiogenesis via pro-angiogenic factors such as interleukin-1 (IL-1), interleukin-8 (IL-8), vascular endothelial growth factor (VEGF), basic fibroblast growth factor (bFGF), tumor necrosis factor α (TNFα) and matrix metalloproteinases 9 (MMP9)." (PMID 32012744, 2020). "Furthermore, TDZ treatment blocked invasion and EMT in non‐tumorigenic BEAS‐2B epithelial cells stimulated with TGF‐β/TNF‐α.TDZ prevents EMT and may thus block metastasis of breast cancer cells." (PMID 33159487, 2020). "Moreover, MUC4 expression in cancer specimens would help select the subgroup of HER2-positive breast cancer patients that benefit from the combination of anti-TNFα therapies with the standard treatments, as we previously demonstrated in HER2-positive breast cancer." (PMID 32391269, 2020). "Serum samples collected before and after the exercise training intervention provided evidence of a reduction in systemic inflammation shown by lower IL-6 and TNF-alpha post-intervention, but these serum samples had no anti-growth effect on the breast cancer cell lines." (PMID 33597950, 2020). "However, to the best of our knowledge, there are no reports showing the participation of TNFα or NF-κB in resistance to EGFR TKIs in breast cancer." (PMID 32391269, 2020). "A nested case-control study in the Malmö Diet and Cancer cohort of postmenopausal women in Sweden found statistically significant negative associations with breast cancer risk for OX-LDL (highest versus lowest tertile: OR 0.63, 95% CI: 0.45, 0.89) and TNF-α (OR 0.65, 95% CI: 0.43, 0.99)." (PMID 32731638, 2020). "Moreover, NLRC4, ASC, and caspase-1 protein levels were induced in response to TNF-α or ATP treatment in a P2Y2R-dependent manner, suggesting that the ATP released by TNF-α treatment activates P2Y2R and regulates inflammasome expression in breast cancer cells." (PMID 32397236, 2020). "In an orthotopic HER2+ murine breast cancer model, tetratherapy induced high levels of antigen-specific T cell responses, tumor CD8+ T cell/Treg ratio, and augmented the presence of IFNγ- or TNFα-producing CD8+ T cells and IFNγ/TNFα bifunctional CD8+ T cells with increased cytokine production." (PMID 33747894, 2020). "Finally, only the high-grade CA1a human breast cancer cell conditioned media positively affected anti-inflammatory IL10 markers in both macrophages, while both CA1h and CA1a conditioned medias upregulated IL10 and downregulated TNFα in monocytes." (PMID 31105883, 2019).
breast carcinoma (continued). "Co-culture of macrophages with breast cancer cells induces sustained release of TNF-α and IL-6 from both cell types, resulting in activation of NF-κB, STAT3, and ERK-1 and hyperphosphorylation of ERα (rendering it constitutively active) in the breast cancer cells." (PMID 30736340, 2019). "Additionally, co-culturing breast cancer cells with mice osteoblasts, it was seen that breast cancer cells were attached to the matrix, produced by osteoblasts, but grew slowly or not at all until TNF-α and IL-β addition." (PMID 31847214, 2019). "In summary, our results establish a critical role for Th1 cytokines, TNF-α and IFN-γ, inducing tumor senescence and apoptosis in breast cancer, and demonstrate a complementary effect with oncogene inactivation that could potentially be applicable to other types of cancers." (PMID 29796172, 2018). "IKKβ interacts with ARD1 in breast cancer cells after TNFα treatment, while IKKα does not." (PMID 30154412, 2018). "The close interplay between the UPR and the TNF pathway, plus recent findings that show that TNF-alpha can prevent in vivo breast cancer development, suggest that downregulation of the TNF pathway in AGR2-overexpressing breast cancers may contribute to their hormone therapy resistance." (PMID 29796176, 2018). "Moreover, the silencing of P65 significantly inhibited the TNF-α-induced HBXIP promoter activities in the cells, suggesting that NF-κB-activated STAT3 is involved in the up-regulation of HBXIP induced by TNF-α in breast cancer cells." (PMID 28938560, 2017). "Given that TNF-α could promote the development of head/neck squamaous cancer and gastric tumor, we concerned whether TNF-α was involved in the progression of breast cancer." (PMID 28938560, 2017). "However, contrary to earlier reports in breast cancer, just no more than 2-fold increase following TNF-α or IL1β treatment." (PMID 28412955, 2017). "Our results may suggest anti-inflammatory effect of estrogen and the lack of induction of aromatase expression by TNF-α, described in breast cancer, in the breast cyst." (PMID 27293305, 2016). "Current evidence suggests that inflammatory cytokines, TNFα and IL-6, increase STS activity, although this has been disputed by a study showing negative correlation between TNFα/IL-6 expression and STS expression in soft tissue breast cancer metastases and primary tumors." (PMID 26213785, 2015). "Similarly, ex vivo production of interleukin-6 (IL-6) and tumor necrosis factor-alpha (TNF-α) by lipopolysaccharide (LPS) stimulated monocytes was higher among fatigued compared to non-fatigued breast cancer survivors." (PMID 26247972, 2015). "However, we did not found any correlation between TNF-α or TNFRSF1A polymorphisms and breast cancer risk." (PMID 25010932, 2014). "It should be noted that either TNFα or PTX3 treatment did not influence RANKT expression in breast cancer cells themselves (data not shown), indicating that PTX3 might be involved in OC formation indirectly." (PMID 24457902, 2014). "Furthermore, TNF-α, IL2, and IL1b have not been associated with fatigue and RT in breast cancer and other malignancies." (PMID 24800238, 2014). "Interestingly, the highly metastatic breast cancer cell line MDA-MD-231 released significantly more ATP than the less metastatic MCF-7 cell line or normal epithelial cells or ECs, and this effect was dramatically enhanced by TNF-α." (PMID 25156554, 2014). "Similar to breast cancer cells, the fraction of incorporation of A375 melanoma cells into ECs was comparable, regardless of whether the ECs were treated with TNF-α." (PMID 25275457, 2014). "In this study, we found that SLC and costunolide inhibit TNFα-mediated breast cancer cell migration and invasion by inhibiting NF-κB activation, thereby suggesting the antimetastatic property of costunolide using highly metastatic MDA-MB-231 breast cancer cells." (PMID 23997800, 2013).